CRP (C-reactive protein)
Diseases named in the same sentence as CRP in open-access papers (continued):
Sharing a sentence is not in itself a finding about the gene and the disease.
malnutrition (continued). "However, after including serum albumin and hs-CRP concentrations (bioindicators of malnutrition and inflammation) in the analysis, the association of fT3 with mortality disappeared." (PMID 36771302, 2023). "It has been shown that an increase in RDW is triggered by nutritional deficiency caused by iron, vitamin B12, and folic acid deficiency and is associated with chronic inflammation and acute phase inflammation markers, such as C-reactive protein, tumor necrosis factor (TNF), and interleukin-6." (PMID 37404429, 2023). "This inflammatory response leads to the secretion of various factors, including cytokines and C-reactive protein, that, in turn, leads to reduced food consumption, weight loss, and diminished muscle function, promoting both malnutrition and sarcopenia in the elderly." (PMID 35439963, 2022). "However, in the setting of high hs-CRP level, a significant risk of all-cause mortality was observed with malnutrition [HR (95% CI):1.66 (1.29–2.14)]." (PMID 35719150, 2022). "We performed a series of multivariate linear regression analyses to evaluate whether there was any relationship between AGEs, RAGEs, and their ratio with inflammatory markers that were mainly associated with malnutrition (i.e., CRP and TNFα)." (PMID 35883745, 2022). "However, concomitant presence of both high hs-CRP level and malnutrition condition were associated with a significantly increased risk of all-cause mortality (HR: 1.51; 95% CI: 1.20–1.89; p < 0.001)." (PMID 35719150, 2022). "However, CRP and age maintained the strongest association with malnutrition (OR 12.13; 95% CI 7.4–20.5; p = 0.001; OR 1.41; 95% CI 1.05–1.23, p = 0.001, respectively)." (PMID 35883745, 2022). "However, concomitant presence of both high hs-CRP level and malnutrition condition was associated with a significantly increased risk of all-cause mortality (HR: 1.51; 95% CI: 1.20–1.89; p < 0.001)." (PMID 35719150, 2022). "Furthermore, in this case, CRP and age were the variables with the strongest association with malnutrition (OR 11.9 95% CI 6.8–20.6, p = 0.001; OR 1.41; 95% CI 1.05–1.23, p = 0.001, respectively)." (PMID 35883745, 2022). "As BCI is directly proportional to CRP levels, its association with malnutrition could also be linked to inflammatory and/or cancer-induced malnutrition and sarcopenia." (PMID 35008333, 2021). "Significant predictors of poor nutritional status were low concentrations of total cholesterol, haemoglobin, HbA1c, ferritin and vitamin D status, and high concentrations of C-reactive protein; except for HbA1c, these were also associated with established malnutrition indicators." (PMID 34072686, 2021). "However, in patients undergoing HD, the serum leptin concentration was significantly and positively correlated with BMI and negatively associated with serum CRP and Malnutrition-Inflammation Score." (PMID 34673824, 2021). "The multivariate model revealed that frailty could be predicted from an increase in age, lower household income, being at risk of malnutrition, wasting (low skeletal muscle mass), and high serum C-reactive protein (CRP) level." (PMID 32916809, 2020). "Elevated CRP-levels are associated with various inflammatory processes, whereas decreased serum albumin levels are associated with chronic diseases and malnutrition and therefore can be a result of chronic inflammatory processes that are known to play a central role in carcinogenesis." (PMID 31788452, 2019). "The role of inflammation as a risk factor for malnutrition has been recognized and it was reported that elevated CRP levels could inhibit albumin synthesis in HD patients." (PMID 31048884, 2019). "Malnutrition and CRP were associated with low plasma selenium." (PMID 24886623, 2014). "According to the results of our study, high levels of CRP in vitamin D deficient patients might be related to other factors such as infectious, inflammatory status, malnutrition, cachexia, or multivitamin deficiency." (PMID 23878538, 2013).
malnutrition (continued). "However, according to the Chinese Standard Operating Procedures for Blood Purification, it is essential to routinely monitor the biochemical indicators and CRP levels in dialysis patients to efficiently and conveniently calculate the malnutrition risk index, known as the CAR." (PMID 41368302, 2025). "According to multiple literature reviews, the factors contributing to malnutrition primarily include disease severity, body mass index (BMI), weight loss, age, food intake, gastrointestinal injury, albumin and hemoglobin levels, muscle mass, and inflammatory markers such as C-reactive protein (CRP)." (PMID 40611154, 2025). "Patients at risk of malnutrition exhibited significantly lower arm circumference (p: 0.000), calf circumference (p: 0.002), lymphocyte counts (p: 0.000), hemoglobin (p: 0.018), albumin (p: 0.001), and BMI (p: 0.038), as well as significantly higher age (p: 0.000) and CRP levels (p: 0.000)." (PMID 40507738, 2025). "However, recently, the Global Leadership Initiative on Malnutrition consensus group has proposed that confirmation of inflammation should be guided by clinical judgement based upon the underlying diagnosis or condition, clinical signs or CRP." (PMID 38783477, 2024). "Other areas to clarify include identification of the best method for calculating baseline weight and which standard methods of measurement of malnutrition might be included in diagnostic criteria (e.g., C‐reactive protein [CRP],34 muscle mass loss, or anthropometric measurements)." (PMID 38982534, 2024). "We found elevated levels of CRP in severely malnourished patients, which has been linked to reduced food intake in acute disease and could therefore be a relevant mechanism leading to malnutrition in CP." (PMID 35719155, 2022). "Moreover, the authors revealed a correlation of nutritional risk with CRP confirming the hypothesis that inflammatory response is a key component of malnutrition and poor outcome in cirrhosis." (PMID 32709104, 2020). "The thesis concerning the impact of inflammation and malnutrition in dialysis patients was confirmed by large, 10-year prospective study of Japanese HD patients which has shown independent association between low TC and higher C-reactive protein (CRP) and mortality in patients with low albumin." (PMID 31752189, 2019). "Therefore, the association between serum TGF-β1 levels and hs-CRP may suggest the degree of vascular inflammation, while correlation with low serum albumin may suggest a state of malnutrition which is very common in CKD patients." (PMID 29977619, 2018). "Therefore, higher levels of C-reactive protein generally suggest an acute infectious or inflammatory process, whereas low albumin is more frequently associated with chronic diseases and is often associated with nutritional deficiency." (PMID 29267535, 2018). "The malnutrition group had lower body weight, body mass index, hemoglobin, albumin, total lymphocyte count, and total protein, as well as higher C-reactive protein levels." (PMID 42152396, 2026). "Another important issue is the use of inflammation biomarkers, such as CRP, as an additional criterion to distinguish IDA from causes other than malnutrition." (PMID 41572874, 2026). "In hematological and gastrointestinal malignancies, elevated C-reactive protein/albumin (CRP/ALB) ratios reflect progressive systemic inflammation and malnutrition, which are strongly associated with shortened overall survival." (PMID 40563367, 2025). "Taken together, the high GPS, characterized by elevated CRP and low albumin levels, reflects significant systemic inflammation, malnutrition, and immune suppression." (PMID 40264786, 2025). "The indirect effect of malnutrition on liver stiffness via CRP was statistically significant (Effect = 0.54, BootSE = 0.20, 95% CI [0.20, 0.95])." (PMID 41463388, 2025). "A low CALLY score (meaning high CRP, low albumin, and low lymphocytes) signifies a state of inflammation with malnutrition and immunosuppression." (PMID 41009701, 2025).
malnutrition (continued). "The figure displays liver stiffness (Y-axis) as a function of CRP levels (X-axis), with separate regression lines for individuals with high (red solid line) and low (blue dashed line) malnutrition." (PMID 41463388, 2025). "In our study, patients with higher malnutrition scores had higher levels of inflammatory markers, such as CRP, IL-6 (Interleukin-6), and IL-10 (Interleukin-10), reinforcing the link between nutritional status and cytokine dysregulation." (PMID 40686821, 2025). "The results indicate that decreased levels of albumin (<3 g/dL) and hemoglobin (<11 g/dL), along with elevated homocysteine, CRP, IL-6 (>7.5 pg/mL), and IP-10 (>250 pg/mL), should alert medical professionals to potential malnutrition in hospitalized patients." (PMID 40094974, 2025). "A multicenter study in Kenya reported that elevated CRP levels, combined with malnutrition, increased the short-term mortality rate in HIV-positive TB patients by 5.6-fold." (PMID 40191188, 2025). "Although CRP levels provide valuable information, our findings suggest that effective personalised malnutrition assessment requires the integration of cancer-specific factors." (PMID 41514593, 2025). "In sum, even near-significant factors (CRP, NRS-2002, Δ-PNI) all trended in a direction consistent with the principle that inflammation and malnutrition predispose to higher mortality." (PMID 41303753, 2025). "COPD studies demonstrate strong correlations between elevated inflammatory markers (e.g., CRP) and appetite suppression/reduced food intake, suggesting inflammation as a critical driver of malnutrition in this population." (PMID 40630494, 2025). "The predictive value of this readily available biomarker is especially relevant in the geriatric setting, whereas systemic inflammation and malnutrition, two key components captured by CRP and albumin, frequently coexist and contribute to adverse outcomes." (PMID 40573094, 2025). "Incorporating CRP into the CALLY index thus enhances its prognostic power by capturing the inflammatory component that often drives the progression of malnutrition and immune dysfunction in geriatric populations." (PMID 41156445, 2025). "Malnutrition (B = 2.29, p < 0.001), MASLD (B = 1.54, p = 0.001), smoking (B = 1.06, p = 0.014), and CRP (B = 0.32, p < 0.001) were independently associated with increased liver stiffness." (PMID 41463388, 2025). "Other commonly used predictors included total body water, calf circumference, phase angle, irisin, upper arm muscle circumference, C-reactive protein, blood phosphorus, severe malnutrition and serum creatinine, which were used twice." (PMID 39752019, 2025). "In clinical practice, we further revealed the relationship between GHRL, MSTN, CRP, and Hs -CRP through correlation analysis, aiming to further elucidate the potential pathophysiological mechanisms between malnutrition/sarcopenia and inflammation." (PMID 40813643, 2025). "Digital ulceration (OR 1.6; 95% CI: 1.3, 1.9; P < 0.01), raised CRP (OR 1.4; 95% CI: 1.1, 1.7; P = 0.01) and PAH (OR 2.0; 95% CI: 1.4, 3.0; P < 0.01) were associated with increased risk of malnutrition." (PMID 38548670, 2025). "In the present study, we used CRP from day 0 (on ICU admission) to day 2 of an ICU stay when a nutritional assessment was performed and examined the utility of CRP for identifying malnutrition and a poor prognosis." (PMID 40005032, 2025). "These collective findings established CRP as a valid inflammatory marker for GLIM-diagnosed malnutrition." (PMID 40871652, 2025). "While increased CRP indicates the severity of the inflammatory response, low albumin levels are generally considered a sign of malnutrition and catabolic processes." (PMID 40005437, 2025). "Although this is a pilot study, we suspect that poor predictive accuracy for CRP is due to the high prevalence of concomitant malnutrition and malaria." (PMID 40569209, 2025).
malnutrition (continued). "Apart from that, CRP is used as an aetiologic criterion for malnutrition diagnosis based on GLIM criteria." (PMID 41463399, 2025). "CRP partially mediated the effect of malnutrition on liver stiffness (indirect effect = 0.54; 95% CI 0.20–0.95), accounting for 18% of the total effect." (PMID 41463388, 2025). "Although low albumin levels are generally associated with malnutrition, we hypothesize that the observed decrease in albumin may be a consequence of negative acute-phase reactant status, as indicated by elevated C-reactive protein (CRP) levels in the malnourished group." (PMID 40507738, 2025). "CRP also reflects systemic cachexia and malnutrition, which directly lead to muscle wasting, fatigue, malaise, reduced performance status, and reduced QoL." (PMID 40385925, 2025). "In line with our results, Ruperto and Barril reported a significant correlation between ECM/BCM and both malnutrition–inflammation score and high sensitivity C-reactive protein (s-CRP) in hemodialyzed patients." (PMID 41340658, 2025). "It is not only reflected by high malnutrition–inflammation scores but also by high levels of inflammatory markers, including high-sensitive C-reactive protein (hs-CRP), ß2-microglobulin, and interleukin (IL)-4 and -6." (PMID 40869417, 2025). "Model 1 was adjusted for age, sex, and BMI; Model 2 was adjusted for Model 1 and presence of ADHF and dementia; and Model 3 was adjusted for Model 2 and inflammation (CRP levels), renal dysfunction (creatinine levels), and malnutrition (albumin levels)." (PMID 40573090, 2025). "Future studies should specifically assess the relationship between inflammation (including CRP) and malnutrition in this population." (PMID 40566551, 2025). "The CRP/Albumin ratio, as an indicator of systemic inflammation and malnutrition, proved to be a significant prognostic biomarker." (PMID 40797479, 2025). "It is said that cancer patients with various tumor types exhibit a typical acute phase protein response, with increased CRP and decreased albumin, leading to high inflammation and malnutrition." (PMID 40647430, 2025). "The horizontal distance between vertical reference lines corresponds to the “a” path (effect of malnutrition on CRP), while the slope of each regression line represents the “b” path (effect of CRP on liver stiffness, controlling for malnutrition)." (PMID 41463388, 2025). "For example, elevated pro‐inflammatory biomarkers such as tumor necrosis factor‐alpha (TNF‐α), interleukin‐6 (IL‐6), and C‐reactive protein (CRP) are commonly seen in cases of malnutrition." (PMID 39817025, 2025). "In our cohort, malnourished patients showed higher CRP levels and lower lymphocyte counts, consistent with the effect of malnutrition on inflammatory status." (PMID 41463388, 2025). "A high CAR value indicates that the patient has an increased CRP or decreased Alb, suggesting a chronic inflammatory response or malnutrition." (PMID 38555313, 2024). "An additional aspect that was included in the present research was the assessment of inflammation (CRP levels), but also malnutrition, through the subjective global assessment (SGA score)." (PMID 39595030, 2024). "High levels of CRP indicate the need for monitoring potential aspiration pneumonia, while low levels of ALB suggest a risk of malnutrition in dysphagia patients." (PMID 38993239, 2024). "In this study, the CONUT 5–12 group exhibited the highest levels of CRP (a marker of malnutrition and inflammation) yet the lowest BMI among the evaluated groups." (PMID 39458457, 2024). "GLIM criteria detected some degree of malnutrition in all diseases requiring LT and identified patients with higher CRP levels and worse respiratory function, anthropometric measurements and visceral protein and lipid profiles." (PMID 38337661, 2024). "It should be noted that results of multivariate analysis showed a significant correlation between malnutrition, CRP, and prealbumin with endoscopic remission." (PMID 39850334, 2024).
malnutrition (continued). "High CRP levels, indicative of systemic inflammatory response, can accelerate protein breakdown, leading to malnutrition." (PMID 39364802, 2024). "The aim of this study was to compare the differences in plasma brain natriuretic peptide (BNP), N‐terminal‐pro B‐type natriuretic peptide (NT‐proBNP), and C‐reactive protein (CRP) in patients with HF and malnutrition versus normal nutrition." (PMID 38850122, 2024). "CRP is also a marker of acute-phase inflammatory response, and low level of albumin indicates malnutrition as well as inflammation severity and disease progression." (PMID 38649407, 2024). "In our study, CRP levels were markedly elevated in patients with HF and malnutrition compared with their non‐malnourished counterparts, demonstrating slightly more pronounced values in the GNRI score." (PMID 38850122, 2024). "Elevated CRP levels hinder nutritional support efficacy also contributing to the early detection of malnutrition." (PMID 39050134, 2024). "The 2018 GLIM standard also uses inflammation indicators (including CRP) as the etiological criteria for the diagnosis of malnutrition." (PMID 39070256, 2024). "Our main analysis according to CONUT scores showed that those will overall malnutrition (n = 2009) had significantly higher levels of CRP versus those with normal nutritional status (n = 454) (k = 4; MD: 0.40, 95% CI 0.08–0.72, I2 = 88%, P = 0.01)." (PMID 38850122, 2024). "The albumin (ALB) level was lower in the malnutrition group than in the non-malnutrition group, while the C-reactive protein (CRP) level was higher; these differences were also statistically significant (P < 0.05)." (PMID 39070256, 2024). "These include elevated CRP levels, low serum albumin levels, hypernatremia, advanced age, malnutrition, comorbidities, and advanced stages of cancer." (PMID 38463403, 2024). "For patients at risk of malnutrition, significant correlations were found at the 0.05 significance level between WBC upon admittance and WBC at discharge (R = 0.45), CRP on admission (R = 0.5), CRP at discharge (R = 0.4), and PCT upon admittance (R = 0.42)." (PMID 38396693, 2024). "In our study, the GLIM criteria allowed us to detect malnutrition in all the diseases requiring LT and to define a population with higher CRP levels and worse respiratory function, anthropometric measurements and visceral protein and lipid profiles." (PMID 38337661, 2024). "The main analysis based on GNRI showed that patients with normal nutrition (n = 679) had significantly lower levels of CRP compared with those with malnutrition (n = 477) [k = 5; MD: 0.50, 95% CI (0.12–0.88, I2 = 87%, P = 0.01)]." (PMID 38850122, 2024). "In patients with ESKD, highly-sensitive CRP and interleukin-6 (IL-6) levels best predict malnutrition, while serum albumin, IL-6, and fetuin A levels best predict mortality." (PMID 37784041, 2023). "Finally, patients at low risk of malnutrition according to all three tools compared to the remaining ones were younger (p < 0.001) and had lower weight and stature, the best scores in all the functional scales (p < 0.001) and the lowest CRP, fibrinogen and D-dimer levels (p < 0.001)." (PMID 37836427, 2023). "It is suggested that in future clinical work, we should pay more attention to postoperative CRP/Alb in gastric cancer patients, and actively take measures to prevent infection and improve malnutrition in order to improve long-term survival of patients." (PMID 37735699, 2023). "Another cross-sectional study was done on 105 HD patients (57.5 years) at Turkish dialysis centers and suggested that DII was significantly correlated with the markers of malnutrition and inflammation (e.g., CRP)." (PMID 37781127, 2023). "Age ≥ 65 years, hs-CRP ≥ 1 mg/L, low ALB, low HB, low BMI, and BWL > 2.4% were independent risk factors for malnutrition in GC patients." (PMID 37293590, 2023).